CXCL12 (C-X-C motif chemokine ligand 12)
Diseases named in the same sentence as CXCL12 in open-access papers (continued):
Sharing a sentence is not in itself a finding about the gene and the disease.
tumor (continued). "The chemokine CXCL12 and its receptors CXCR4 and CXCR7 are involved in how tumor cells are released from the primary tumor and find their metastatic sites." (PMID 36358665, 2022). "Inhibition of angiotensin or CXCL12/CXCR4 signaling, targeting extracellular collagen, hyaluron, and CAFs, improves perfusion and decompression of tumor vessels and has a positive impact on ICB." (PMID 36140392, 2022). "Immature DCs can be recruited into the TME, attracted by tumor-secreted factors such as CCL2, CCL20/MIP3a, CCL25, CCL5, CXCL12, CXCL1, and CXCL5, while mature DCs reside in areas surrounding the tumor." (PMID 35267487, 2022). "Tumor/fibroblast interaction has been involved the progression of cancer, the CXCR4/CXCL12 chemokine axis being a main leader of malignancy." (PMID 35406582, 2022). "The CXCL12/CXCR4 axis can transactivate HER2 and promote intraosseous tumor growth in prostate cancer." (PMID 36254250, 2022). "Despite the intimate crosstalk between the CXCL12- and CXCL11-system, the impact of a combination of CXCL12 and CXCL11 on tumor progression remains vague." (PMID 36539774, 2022). "To further illustrate this, we compared the trajectories of CXCL12, a key regulator of EMT and tumor invasion in the PID and ACSN Cadbiom models." (PMID 35696426, 2022). "In the context of targeting CAFs in relation to the hypoxic tumor microenvironment, TGF-β, HIF, and CXCL12/CXCR4 signaling pathways are perhaps the most promising targets." (PMID 35884382, 2022). "The CXCL12/CXCR4 axis mediates the metastasis and homing of immune cells at tumor sites, thus affecting the specific immune response." (PMID 35893797, 2022). "In addition, our study revealed that MXRA8 expression correlated with the expression of multiple metastasis-associated chemokines (CXCL12, CXCL13, CCL9, CCL21, CXCR4, CXCR5, and CCR7), suggesting that MXRA8 may be involved in tumor invasion and metastasis by regulating the secretion of chemokines." (PMID 36703779, 2022). "CXCL12 and CXCR4 within the TME generally promote tumor angiogenesis and the survival and proliferation of tumor cells; they also recruit immune cells and direct them to specific immunosuppressive responses." (PMID 35565443, 2022). "CXCL12 neutralization abolished the 7HP349 treatment–related increase in frequencies of CD8+ and CD4+ Teffs and tumor myeloid cell infiltrates consisting of IMs, granulocytes, M1 macrophages, M2 macrophages, pDC, and cDC2." (PMID 35552271, 2022). "A variety of chemokines and chemokine receptors are correlated with cancer cell metastasis, and CXCL12/CXCR4 axis is a key representative system, which participates in the metastasis of various tumor cells." (PMID 35770088, 2022). "The CXCL12/CXCR4 axis can also induce vascular endothelial growth factor (VEGF) expression through the JAK2/STAT3 pathway, inducing tumor angiogenesis." (PMID 35893797, 2022). "For example, SNHG17 exerts a pro-tumor effect in CRC by sponging miR-23a-3p and upregulating CXCL12." (PMID 35248073, 2022). "First, hypoxia‐triggered release of chemoattractants (i.e., CCL2, CCL5, CXCL12, CSF‐1, and VEGF) from tumor cells and non‐tumor cells to enhance TAMs precursor monocytes recruitment." (PMID 37323705, 2022). "In BlCa, IL-6, CCL2, CXCL1, CXCL12, IL-8 and TGF-β1 play putative roles in promoting tumor progression, growth, invasion, and metastases formation." (PMID 36699696, 2022). "FAK signaling create the immunosuppressive TME by regulating the expression of chemokines such as CXCL12 and CCL5, enabling tumors to escape anti-tumor immunity." (PMID 35425701, 2022). "CAFs, in contrast, express paracrine molecules that promote tumour growth and therapy resistance, including growth factors (CTGF, EGF, and PDGF), chemokines (CXCL1, CXCL5, CXCL7, CXCL8, CXCL12, and CCL12), and cytokines (IL-6, IL-11, and LIF)." (PMID 36284087, 2022).
tumor (continued). "All tumor cells showed statistically significant migratory responses to CXCL11 at concentrations as low as 1 ng/ml, whereas with CXCL12 at 1 ng/ml statistically significant migratory responses only occurred with A549 and A767 cells." (PMID 36539774, 2022). "CXCR4 and its chemokine ligand 12 (CXCL12), also known as the stromal cell-derived factor-1 (SDF-1), are two key factors in the cross-talking between tumor cells and their microenvironment." (PMID 35877436, 2022). "CXCL12 is also reported to promote the infiltration and mobilization of FOXP3+ tumor-infiltrating lymphocytes to enhance protumoral immunity." (PMID 35740551, 2022). "In pancreatic ductal adenocarcinoma (PDAC), the CXCL12/CXCR4 axis mediates the desmoplastic reaction; this changes the tumor mechanical microenvironment and promotes drug resistance." (PMID 35893797, 2022). "In another study, it was observed that endothelial progenitor cells are recruited via TAF mediated SDF-1/CXCL12 release and signalling that can also lead to angiogenesis in growing tumours." (PMID 35814453, 2022). "As the amount of CXCL12 expression increases, the amount of CXCR4 increases in endothelial cancer cells in the tumor microenvironment and affects the cells forming spheroids." (PMID 36551144, 2022). "In fact, CAFs directly enhance tumor angiogenesis through producing pro-angiogenic factors like vascular endothelial growth factor A (VEGFA), fibroblast growth factor 2 (FGF2), CXCL12, and PDGFC." (PMID 36465388, 2022). "The CXCR4/CXCL12 (SDF-1) axis enhances metastasis by mediating the migration and proliferation of tumor cells and inducing angiogenesis via the Akt signaling pathway." (PMID 36499667, 2022). "In combination with radiotherapy, antagonists to CXCL12, CXCR4 and CXCR7 have led to complete brain tumor regression and survival prolongation of tumor-bearing rodents." (PMID 36568151, 2022). "HIF1α overexpression can trigger tumor cells to secrete chemoattractants, including stromal-derived factor 1α (SDF-1α or CXCL12), CXCL5, and CCL2." (PMID 36419156, 2022). "Growth factors such as HGF, VEGF, EGF, CTGF, IGF, and NGF, cytokines such as IL-6, IL-11, and IL-17, and chemokines such as CCL7, CCL5, CXCL12, and CXCL7 are produced by CAF in the process of interaction between tumor cells and CAF." (PMID 36293435, 2022). "Our previous work revealed that CXCL12 and CXCL11 promote tumor cell migration with equal potency and further demonstrated that in most tumor cells these migratory responses involve either CXCR7 alone or CXCR7 in combination with another chemokine receptor." (PMID 36539774, 2022). "In 4 out of 5 tumor cell types (A549, A767, DLD-1, MDA-MB-231) CXCL12 and/or CXCL11 induced a slight, but in most cases statistically significant increase in apoptotic cell numbers." (PMID 36539774, 2022). "The resulting CX43/CXCL12/CXCR4 interaction boosted mitochondrial trafficking in MSCs and protected tumor cells from the effects of anti-myeloma drugs." (PMID 35958625, 2022). "CXCL12 and CXCL11 were almost equally potent in inducing migration of the various tumor cells, resulting in a dose-dependent, maximal 2.5–3.5-fold increase of the migration index." (PMID 36539774, 2022). "The hypoxic tumor microenvironment can favor the upregulation of CXCR4 and CXCL12 in several cell types such as endothelial cells and cancer cells through mobilization of the hypoxia induced factor 1 (HIF-1α)." (PMID 35406582, 2022). "The combination of CXCL12 and CXCR4 can activate signaling pathways such as MAPK/ERK, PI3K/Akt/NF-κB, and c-Jun N-terminal kinase and regulate tumor progression." (PMID 35647303, 2022). "Hypoxia induces tumor cells and stroma to produce cytokines, such as CCL2 (C–C motif chemokine ligand 2), CXCL12 (C-X-C Motif Chemokine Ligand 12), CSF1 (Colony Stimulating Factor 1) and VEGF to recruit macrophages." (PMID 35361234, 2022).
tumor (continued). "Concomitantly, higher expression of CXCL12 and CXCL11 was found in tumor areas in the lung compared with the liver, indicating that distinct pathways regulate the mechanism of pulmonary and hepatic metastatic spread." (PMID 35406582, 2022). "In GC tissues, CXCL12/CXCR4, highly overexpressed, is tightly correlated with the metastasis of lymph nodes, higher tumor, node, metastasis staging, and poor prognosis." (PMID 35647303, 2022). "Through a combination of spatial profiling and scRNA-seq analysis, we found evidence suggestive of increased pericyte coverage within the Eml4-Alk tumor vasculature, potentially mediated by altered paracrine signaling via PDGF and CXCL12." (PMID 36192379, 2022). "Despite the established interaction between the CXCL12- and CXCL11-systems, combined effects of both chemokine systems on tumor growth and metastasis are still ill defined." (PMID 36539774, 2022). "Immature DC can be recruited to the TME by tumor-derived factors such as VEGF, HGF, b-defensin, CXCL8, and CXCL12." (PMID 36419156, 2022). "CXCL12 is secreted by CAFs and coats PDAC tumor cells, since the malignant cells express higher levels of CXCR4 compared to normal pancreas tissue." (PMID 36077755, 2022). "For example, CXCL12 secreted by PSCs significantly reduces the migration of CD8+T cells to the peripheral stroma of pancreatic cancer, resulting in reduced anti-tumor activity of effector T cells." (PMID 35965504, 2022). "Conversely, FAT-WT patients had suppressive TME with high expression of CCL2, CXCL12, CXCL14, CD40, ENTPD1, TGFB1, and VEGF; these factors have been confirmed to promote angiogenesis, invasion, and metastasis of tumor cells." (PMID 35836939, 2022). "We observed increased migration of NK cells towards CHMP2A KO tumor cells that showed increased secretion of CXCL10 and CXCL12, chemokines involved in NK cell migration." (PMID 35393416, 2022). "The presence on the cell surface of CXCL12 and KRT19 was confirmed by flow cytometric analysis of single-cell suspensions of intact tumor cells." (PMID 35046049, 2022). "CXCL12 produced by CAFs recruits CXCR4-expressing endothelial progenitor cells and immune suppressive Tregs, which contributes to angiogenesis and tumor growth." (PMID 36010899, 2022). "Data on combined effects of CXCL12 and CXCL11 on the tumor microenvironment are at present unavailable." (PMID 36539774, 2022). "It has been reported that, in primary HNSCC tissues, tumor cells produce a high level of CXCL12/SDF-1 and CXCL14, which promote the infiltration of tumor-infiltrating lymphocytes and pDCs." (PMID 35740551, 2022). "CXCL12 interacts also with the CXCR4 present on the surface of mature B cells and mediates the recruitment of B regulatory cells to the tumor site inhibiting T cell activity." (PMID 35565443, 2022). "TAMs can express VEGF, TGF-β, angiogenesis chemokine CXCL12, and platelet-derived growth factor (PDGF), which promote the formation of partial blood vessels and lymphatic vessels of tumor and even further tumor invasion and migration." (PMID 36311793, 2022). "We found that the expression level of ADARB1, CXCL12 and TABPB were higher in recurrent tumor tissues, whereas the expression level of B2M was lower in recurrent tumor tissues." (PMID 35177985, 2022). "CHMP2A-knockout (KO) tumor cells secrete more CXCL10 and CXCL12, increasing NK cell migration in vitro." (PMID 35393416, 2022). "CXCL12 is an important chemokine, and high levels of it in TIME can recruit highly tumorigenic tumor cells and promote their proliferation, angiogenesis, and metastasis." (PMID 35401551, 2022). "CXCR4, a hypoxia-inducible chemokine receptor, interacts with CXCL12 to suppress CD8-positive cytotoxic T cells, thereby supporting immune evasion of tumor cells." (PMID 35884382, 2022). "Solid tumors produce chemokines like CXCL1, CXCL12, and CXCL5 within the TME, preventing T cells from reaching the tumor cells." (PMID 35844304, 2022).
tumor (continued). "Macrophages represent the first type of immune cells frequently detected in the tumor microenvironment and classically derive from circulating monocytes attracted by chemokines such as CCL2, CXCL5, and CXCL12 secreted by tumors." (PMID 36230504, 2022). "Tumor PCs also increased CX43 expression in MSCs, and led to an elevated CXCL12 expression and stimulated CXCR4 expressed on MM cells." (PMID 35958625, 2022). "The stromal cell-derived factor-1 (CXCL12) activates CXC chemokine receptor-4 (CXCR4) and promotes tumor cell migration as well as invasion." (PMID 35910383, 2022). "Hypoxia is the main driver of EPCs homing at the tumor site—this induces, via HIF-1α expression, numerous growth factors, cytokines, and chemokines, including VEGF-A, CXCL12, and CXCR4." (PMID 35203510, 2022). "Immunohistological assays were applied to validate the expression of CXCL12, PDGFRA and VIM in normal and tumor tissues." (PMID 34801033, 2021). "The interaction of CXCL12 with CXCR4 and the subsequent signal transduction plays an important role in tumor progression and metastasis." (PMID 34833360, 2021). "CCL-2 and CXCL-12 can aid in angiogenesis and impede endothelial cells' apoptosis through straight receptor (CXCR-4 and CCR-2) binding on tumour vessels or obliquely propping up drafting in leukocytes." (PMID 34336101, 2021). "Osteoblasts as a cellular source for C-X-C motif chemokine 12 (CXCL12, also known as stromal cell-derived factor 1, SDF1) are also important for tumor cell homing to bone." (PMID 34064859, 2021). "We further demonstrated that knockdown of CTNND1 not only enhanced intrinsic metastatic functions including migration and invasion, but also facilitated tumor recruitment to bones, an event through the CXCR4/CXCL12 axis by activating PI3K/AKT/HIF-1α pathway." (PMID 34830862, 2021). "In contrast, analysis of immune-fibroblast interactions highlighted CXCL12 expression by fibroblasts, with the potential to recruit CXCR3/4-expressing CD8 T cells and MNPs that was reduced in tumor." (PMID 34936871, 2021). "We confirmed the control of the main chemokine/receptor axes, CXCL12/CXCR463 and CCL21/CCR7,11, 64 involved in tumour escape and verified their dependency on hypoxia." (PMID 33624446, 2021). "CXCL12, which led to PI3K and ERK1/2 activation in tumour cells, and CCL2, which was released by stromal cells and tumour cells to recruit myeloid cells, exhibited significantly increased expression in the exhausted groups than in the active groups." (PMID 34059019, 2021). "CXCL12, and its receptor C-X-C receptor 4 (CXCR4), are related to hematopoiesis, angiogenesis, stem cell homing, and tumor progression and behavior." (PMID 34063285, 2021). "In AML, CSCs express CXCL12 and CXCR4, with CXCL12 being a promoter of CSC survival and tumor repopulation by regulating the interaction with the stromal microenvironment." (PMID 33530455, 2021). "Tumor cells that maintain CXCR4 overexpression, but lack CXCL12 expression, can be directionally transferred to target organs with high levels of CXCL12 secretion." (PMID 33710803, 2021). "Tumor-conditioned monocyte shown an increased migration in response to CXCL5, CXCL12, CCL3, and CCL5." (PMID 34975843, 2021). "Silencing of CXCL12 altered the homeostatic autocrine and paracrine CXCR4 signaling to endocrine communication in the tumor microenvironment, leading to tumor progression and metastases." (PMID 34321012, 2021). "Additionally, CCR4/CCL17 or 22 and CXCR4/CXCL12 are vital chemokine signalling pathways for the recruitment of immune cells (regulatory T cells (Tregs), neutrophils and dendritic cells (DCs)) and participate in the metastatic colonization of tumour cells as well." (PMID 35006432, 2021). "Recently, the chemokine CXCL12 and its receptor CXCR4 have emerged as promising drug targets due to their crucial roles in the tumor microenvironment and trafficking of immune cells." (PMID 33456563, 2021).
tumor (continued). "We found that cabozantinib treatment significantly upregulated CCL11, CCL12, CXCL12, CCL8 and CX3CL1 in the tumor microenvironment." (PMID 33954115, 2021). "Of the various chemokine signaling networks, the C-X-C Motif Chemokine Ligand 12 (CXCL12)/CXCR4 axis is recognized as a prominent moderator of the supportive tumor microenvironment (TME) and tumor-stroma interactions." (PMID 34453639, 2021). "Here, similarly to HSC recruitment, CXCL12/CXCR4 signaling is one of the main stimulatory axes attracting CTCs to home to and to adhere within bone, and also supports tumor cell survival and dormancy as well as angiogenesis." (PMID 34064859, 2021). "Tumor-conditioned monocytes presented similarities with ncMO phenotype from DLBCL and were prone to migrate in response to CCL5 and CXCL12, and presented similarities with DLBCL-infiltrated myeloid cells, as defined by mass cytometry." (PMID 34975843, 2021). "CXCL12 itself activates numerous signaling pathways, including the PI3K/Akt and Ras/Raf/MAPK pathways that promote tumor progression (11, –13)." (PMID 33753481, 2021). "In general, CAFs secrete major cytokines including TGF-β1, C-X-C motif chemokine ligand 12 (CXCL12), platelet-derived growth factor (PDGF) and interleukin-6 (IL-6) which promote tumor growth and metastasis." (PMID 34638283, 2021). "CXCL-12 is a chemokine that acts through CXCR4 and plays an essential role in tumor invasion and metastasis in numerous cancer types." (PMID 33390169, 2021). "In PDAC, overexpression of SDF-1/CXCL12 has often been reported, at least in part, mediated by the production of the hypoxic inducible factor (HIF) in the hypoxic tumor environment." (PMID 34764871, 2021). "cSCC tumors that tend to be deeper and more advanced also significantly upregulate CXCR7, which signals through CXCL12 to promote ERK signaling, thus prolonging tumor cell survival." (PMID 34122442, 2021). "Blockade of CXCR4, the receptor of CXCL12, enhanced macrophage and CD8 TIL infiltration and reduced tumor growth and subsequent metastasis." (PMID 33988305, 2021). "TAM-derived prostaglandin E2 (PGE2) initiates the production of CXCL12, which induces myeloid-derived suppressor cell (MDSC) accumulation and inhibits the production of CXCL10, a chemokine that activates anti-tumor immunity." (PMID 34209703, 2021). "Biochemical analyses further demonstrate that CXCL12 supports KRAS-induced MAPK and AKT signaling to promote tumor cell survival and proliferation." (PMID 35008248, 2021). "Gene expression analysis reveals increased expression of C‐X‐C motif chemokine ligand 12 (CXCL12) and colony stimulating factor 1 (CSF1) in senescent tumor cells." (PMID 33643790, 2021). "As stated in the preceding section, the CXCL12/CXCR4 axis plays a crucial role in bone metastasis and the interaction between tumor cells and bone cells." (PMID 34064589, 2021). "CXCL12 can activate the PI3K/AKT signaling pathway in tumor cells, upregulate the expression of VEGF in tumor tissues, and promote angiogenesis." (PMID 34447750, 2021). "The results showed that the relative expression of CXCL12, CEBPA, and TUBA1A in tumor cells was significantly lower than that in normal cells (all P < 0.05)." (PMID 34225733, 2021). "CXCL12 promoter hypermethylation downregulates CXCL12 protein expression in PC, disrupting the cellular feedback internalization of membranous CXCR4 and so favoring tumor cell motility and metastatic potential." (PMID 34830196, 2021). "PGE2 can also stimulate the expression of CXCL12 via the EP3 receptor, which increases the accumulation of CXCR4 + tumor cells and promotes the formation of the LN pre-metastatic niche." (PMID 34241649, 2021). "CXCR4 selectively binds with stromal cell-derived factor 1 (SDF1), also known as C-X-C family chemokine ligand 12 (CXCL12) (CXCL12/SDF-1), which induced tumor proliferation and metastasis." (PMID 34220311, 2021).